ENPP1 (ectonucleotide pyrophosphatase/phosphodiesterase 1)
Diseases named in the same sentence as ENPP1 in open-access papers (continued):
Sharing a sentence is not in itself a finding about the gene and the disease.
cancer (continued). "We reason that APC recruitment and education at the initial site of cancer encounter is important in mounting a successful adaptive immune response, and this process appears to be diminished when tumors overexpress ENPP1." (PMID 38117852, 2023). "As an alternative strategy, direct injection of cGAMP in the tumors has been studied, especially in the context of cancer vaccines (see section II.2) but it is limited by the presence of ENPP1." (PMID 37287967, 2023). "Taken together, the specific binding to cell membrane associated ENPP1 by these antibodies warrant their further development as targeting modules in ADC, IbTEs and CAR-Ts for immunotherapy against ENPP1 overexpressing cancers." (PMID 36761762, 2023). "It has been shown that ENPP1 is increasingly up-regulated as cancer cells become metastatic, and this enhances cancer cell migration in a cGAS-dependent manner." (PMID 37534795, 2023). "We then tested ADC killing effects on HepG2 cancer cells that natively express ENPP1, though HepG2 cells display lower expression of ENPP1 than the 293T-ENPP1 cell line." (PMID 36761762, 2023). "Taken together, these anti-human ENPP1 antibodies show significant promise as antibody–based immunotherapy candidates for cancers that express high levels of ENPP1." (PMID 36761762, 2023). "To understand the mechanisms of cancer-derived ENPP1 overexpression in driving immunosuppression, we first analyzed expression of genes in the extracellular cGAMP–STING pathway." (PMID 38117852, 2023). "Using an unbiased scRNA-seq approach, we systematically characterized the immunological impacts and signaling events upon overexpression of ENPP1’s catalytic activity in orthotopically implanted 4T1 cancer cells." (PMID 38117852, 2023). "Ectonucleotide pyrophosphatase/phosphodiesterase 1 (ENPP1) expression has been correlated with poor cancer prognosis with unclear mechanisms." (PMID 38117852, 2023). "We developed a potent in-house ENPP1 inhibitor, AVA-NP-695, to study the effects of ENPP1 inhibition on various therapeutic aspects of cancer." (PMID 36235254, 2022). "ENPP1, a gene with the function of hydrolyzing the extracellular cGAMP was increasingly expressed in cancer cells with genomic instability." (PMID 36518306, 2022). "Herein, we demonstrate that AVA-NP-695, a selective and highly potent ENPP1 inhibitor, apart from the immunomodulatory effect also modulates cancer metastasis by negatively regulating epithelial–mesenchymal transition (EMT)." (PMID 36235254, 2022). "At first, the ENPP1 expression was analyzed using The Cancer Genome Atlas Program (TCGA) pan-cancer datasets." (PMID 36235254, 2022). "We also observed decreased expression of ENPP1, with known roles in cancer invasion and metastasis, as well as STING pathway upregulation." (PMID 35365682, 2022). "The gene and protein expression levels of ENPP1 have been reported to be upregulated in several cancer types." (PMID 36235254, 2022). "ENPP1 expression levels across cancer cell lines (CCLE datasets) were also analyzed to find the concordance of ENPP1 expression between patient samples and cell lines." (PMID 36235254, 2022). "Only a combination of 2′3′-cGAMP and ENPP1 inhibitor—in this case, AVA-NP-695—is able to restore the EMT levels, thus highlighting the importance of ENPP1 inhibitors in high-ENPP1 cancer." (PMID 36235254, 2022). "On one hand, ENPP1 inhibitors are capable of maintaining cellular endogenous cGAMP levels to inhibit cancer migration and metastasis." (PMID 35806118, 2022). "By increasing STING activation and lengthening the half-life of cGAMP in mice that have ENPP1 knocked out, inhibiting ENPP1 has emerged as a promising strategy for cancer immunotherapy." (PMID 36234712, 2022). "Studies have shown that aberrantly expressed ENPP1 participates in the pathogenesis and therapeutic response of human cancers, including ovarian cancer, glioma, and breast cancer." (PMID 36199794, 2022).
cancer (continued). "This study provides new insight into the designing of novel ENPP1 inhibitors and warrants further development of small molecule immune modulators for cancer immunotherapy." (PMID 36069240, 2022). "ENPP1 (ectonucleotide pyrophosphatase/phosphodiesterase 1) has been proved to induce the stemness features of cancer cells." (PMID 34476219, 2021). "ENPP1 is an enzyme that can hydrolyze the extracellular cGAMP, preventing its transfer from cancer cells to the microenvironment, thus avoiding its transfer to immune cells." (PMID 35008251, 2021). "Ectonucleotide pyrophosphatase/phosphodiesterase 1 (ENPP1) is an emerging therapeutic target in human cancers owing to its role in degrading cyclic GMP-AMP (cGAMP), an agonist of the stimulator of interferon genes (STING)." (PMID 32876064, 2020). "Structures of the cancer target human ENPP1 have been determined in the apo form, bound to nucleotides and bound to known inhibitors of the enzyme." (PMID 32876064, 2020). "This review highlights the roles played by ENPP1, the mechanism of cGAMP hydrolysis by ENPP1, and small molecule inhibitors of ENPP1 with potential applications in diverse disease states, including cancer." (PMID 31752288, 2019). "Because upregulation of miR-27b reduced the tumourigenic SP fraction and ENPP1 was expressed at a high level in this fraction, these results indicate that ENPP1 contributes to the acquisition of resistance to anti-cancer agents." (PMID 26065921, 2015). "Cancer types showing significant correlations between ENPP1 expression and HRD score." (PMID 41496120, 2026). "This dual action makes ENPP1 a compelling target in the landscape of cancer immunotherapy." (PMID 38881902, 2024). "However, even where cancer cells lack Enpp1, stromal expression of Enpp1 and particularly macrophage Enpp1 expression can degrade cGAMP and result in decreased cGAMP availability for innate activation." (PMID 39622844, 2024). "Nonetheless, it is unknown whether quercetin is capable of inhibiting ENPP1, a property that would hold great therapeutic potential for pseudogout, soft tissue calcification and various cancers." (PMID 38167594, 2024). "If cancer cell expression is essential, it may be necessary to test each patient for cancer cell expression of Enpp1 to justify this intervention." (PMID 39622844, 2024). "The inhibition of ENPP1 presents a promising avenue for cancer therapy." (PMID 38881902, 2024). "Endothelial cells, on the other hand, do not express measurable levels of Enpp1, which could explain the predominant effect of cancer-derived ENPP1 on their STING activation profile." (PMID 38117852, 2023). "Researchers are currently investigating the clinical utility of ENPP1 inhibitors in many cancers." (PMID 38435029, 2023). "As a central player dictating cancer-innate-adaptive immune communication through the STING pathway, ENPP1 is a promising target for cancer immunotherapy that may bolster our arsenal of ICB therapeutics as a druggable innate immune checkpoint." (PMID 38117852, 2023). "Thus, these various antibody-derived modalities are promising therapeutic candidates for cancers expressing human ENPP1." (PMID 36761762, 2023). "Previous studies and our analysis so far have focused on ENPP1 expressed by cancer cells." (PMID 38117852, 2023). "Overall, the current research shows that ENPP1 could serve as a powerful target for treating a wide range of cancers." (PMID 36761762, 2023). "Future examination of ENPP1 in other mouse cancer models and patient cohorts are warranted to test these hypotheses." (PMID 38117852, 2023). "ENPP1 expression levels have been shown to correlate with poor prognosis in several cancer types." (PMID 38117852, 2023). "This raises the exciting possibility that ENPP1 inhibitors could act synergistically with MerTK blockade to clear cancer (see section I.1.4)." (PMID 37287967, 2023).
cancer (continued). "Hence, these data delineate an interesting aspect of ENPP1 upregulation as cancer metastasizes, probably to destabilize the endogenous 2′3′-cGAMP, which can negatively regulate EMT via the Wnt/ꞵ-catenin pathway." (PMID 36235254, 2022). "It is pivotal and significant to develop ENPP1 inhibitor for cancer immune therapy." (PMID 34677780, 2022). "Emerging studies have shown aberrant ENPP1 in cancer pathology." (PMID 36199794, 2022). "ENPP1 thus represents an attractive target in cancer therapies." (PMID 32876064, 2020). "In addition to being a target for bone, cardiovascular, and metabolic diseases, ENPP1 has now emerged as a therapeutic target for cancers." (PMID 31752288, 2019). "Clearly, ENPP1 inhibitors would play an important role in cancer immunotherapy." (PMID 31752288, 2019). "As HER2 and ENPP1 are overexpressed in OS, a bispecific molecule combining the ENPP1 inhibitor with a second clinical antibody such as trastuzumab could be an opportunity to treat this aggressive cancer." (PMID 37400538, 2024). "In addition, through a combined impact on cancer cell and stromal Enpp1, patients with low Enpp1 expression may be more responsive to PD1 inhibition as part of multimodality therapy." (PMID 39622844, 2024). "Hence, ENPP1 is a potential target for immunotherapy across multiple cancers." (PMID 36761762, 2023). "Consequently, ENPP1 inhibitors have emerged as an attractive approach for cancer therapy." (PMID 35365682, 2022). "Notably, the virtual screening methods used in this study will also be helpful to discover novel ENPP1 inhibitors of other chemical skeletons, which may further be used in cancer immunotherapy." (PMID 36234712, 2022). "Furthermore, we have identified three genes implicated in cancer metastasis – MMP13, ST6GAL2, and ENPP1, which pazopanib has demonstrated to downregulate in our study and could act as drug-response biomarkers or a druggable target with regards to the latter." (PMID 35365682, 2022). "As the relationships between ENPP1 expression and HRD score across pan-cancer samples appeared heterogeneous, we applied linear regression-based clustering to identify multiple plausible linear patterns between ENPP1 expression and HRD score." (PMID 41496120, 2026). "In this study, we comprehensively investigated the relationship between ENPP1 expression and HRD scores, and their molecular and clinical significance in pan-cancer samples." (PMID 41496120, 2026). "Despite the increasing significance of ENPP1 and HRD in cancer biology and treatment, their potential relationships have not yet been comprehensively investigated." (PMID 41496120, 2026). "In this study, using The Cancer Genome Atlas (TCGA) dataset, we investigated the relationship between ENPP1 expression and HRD scores across multiple cancer types and assessed their molecular and clinical significance." (PMID 41496120, 2026). "Pharmacological inhibition of NPPS-HK1 axis using NPPS inhibitor Enpp-1-IN-1 or HK1 inhibitor 2-deoxyglucose (2-DG), or genetic interfere with NPPS suppressed RAS-mutant cancers in vitro and in vivo." (PMID 39506063, 2025). "In this review, we discuss about various small molecule modulators of targets such as STING/ENPP1, TLR, NLRP3, and SIRPα-CD47 which are key players in the innate immune system working against cancer." (PMID 39318624, 2024). "Selectively abolishing the cGAMP hydrolysis activity of ENPP1 phenocopied ENPP1 knockout in a STING-dependent manner, demonstrating that restoration of paracrine cGAMP–STING signaling is the dominant anti-cancer mechanism of ENPP1 inhibition." (PMID 38117852, 2023). "Ectonucleotide pyrophosphatase/phosphodiesterase 1 (ENPP1) has been discovered as the principal hydrolase for cGAMP and thus, ENPP1 restrains innate immune responses to cancer." (PMID 36069240, 2022).
cancer (continued). "ENPP1 was subsequently shown to be a negative regulator of anticancer innate immunity, enabling the development of ENPP1 inhibitors (patents WO2020160333A1, WO2019023635A1, WO2018119328A1) as investigative new drugs for cancer therapy." (PMID 35588451, 2022). "In line with previous observations, genes involved in cancer development were represented on Bs of four studied species: red fox (KIT), Chinese raccoon dog (ENPP1, GNAS, HMGCR, KDR, RET), brocket deer (BCL6, RASA1, RET), and Korean field mouse (JAK3)." (PMID 30103445, 2018). "Interestingly, we and others reported that ectonucleotide pyrophosphatase/phosphodiesterase family member 1 (ENPP1), an ectonucleotidase in the TME which hydrolyses cGAMP to AMP in a parallel pathway, is upregulated in chromosomally unstable cancers." (PMID 40379112, 2025). "Interestingly, in chromosomally unstable cancers like those containing BRCA1/2 PVs, ectonucleotide pyrophosphatase/phosphodiesterase 1 (ENPP1) has been shown to be upregulated." (PMID 39682099, 2024). "Together, these data confirm a lack of Enpp1 protein and function in the cancer cells, supporting the RNASeq-based data." (PMID 39622844, 2024). "In addition, the synergistic effects of the combination of ENPP1 inhibitors and the STING agonist, cGAMP, should be studied for its therapeutic potential in cancer." (PMID 35806118, 2022). "For example, while GMPR and ENPP1 interact simply through the KEGG purine metabolism pathway, the APC-FZD3 interaction involves three different pathways: KEGG basal carcinoma, KEGG pathways in cancer, and KEGG wnt signaling pathway." (PMID 27378931, 2016). "Together these data suggest that macrophages in tumors express Enpp1 and this may limit cGAMP availability and subsequent immune activation even in tumors where cancer cells do not express Enpp1." (PMID 39622844, 2024). "Moreover, among deadly cancers, AML cells exhibited the highest cGAS and lowest ENPP1 levels." (PMID 38413714, 2024). "To test whether Enpp1-targeted therapies could improve the response to RT in wild type mice where the cancer cells do not express Enpp1, we developed a novel orally bioavailable Enpp1 inhibitor, VIR3." (PMID 39622844, 2024). "This suggests that Enpp1 inhibition may be an effective partner for radiation therapy regardless of whether cancer cells express Enpp1." (PMID 39622844, 2024). "The interaction between ENPP1 expression and HRD score appeared dynamic, context-dependent, and integrated into core cancer hallmarks rather than being fixed or isolated." (PMID 41496120, 2026). "Our work demonstrates that ENPP1 and ENPP3 non-redundantly dampen extracellular cGAMP-STING signaling, pointing to ENPP3 as a target for cancer immunotherapy." (PMID 38749434, 2024).
genetic disorders (9 papers, 2016 to 2024). "Loss-of-function mutations in ENPP1 have been associated with a rare genetic disease that causes ectopic calcification in neonatal life in humans." (PMID 39454569, 2024). "Most recent theories refer to GACI as a genetic disease that might be caused by mutations in the ectonucleotide pyrophosphatase/phosphodiesterase 1 gene (ENPP1)." (PMID 36061401, 2022). "Remarkably, when ENPP1 or CD73 are mutated and non-functional this leads to other inherited diseases called General Arterial Calcification of Infancy (GACI) and Calcification of Joints and Arteries (CALJA), with overlapping symptoms." (PMID 38392293, 2024).
infection (9 papers, 2013 to 2023). The state of being infected such as from the introduction of a foreign agent such as serum, vaccine, antigenic substance or organism. "The expression of ENPP1-MF in stable transfectants was confirmed by immunoblotting at day 7 after infection." (PMID 26065921, 2015).
cardiovascular disease (4 papers, 2007 to 2022). "Variants in the ENPP1, ABCC6 and 5'-nucleotidase ecto (NT5E) genes, which are involved in metabolism of PPi and Pi, have been found to predispose to coronary arterial, valvular calcification and other cardiovascular diseases." (PMID 35387434, 2022).
metabolic disease (4 papers, 2013 to 2023). A congenital disorder (due to inherited enzyme abnormality) or acquired (due to failure of a metabolically important organ) disorder resulting from an abnormal metabolic process. "In addition, as suggested by recent studies on ENPP1 rs1044498, a deeper knowledge of the genetic variants affecting the pathogenesis of T2D and related metabolic diseases may have important implications also for the implementation of tailored therapeutical approaches." (PMID 23762820, 2013).
immune diseases (2 papers, 2019 to 2025). "In order to speculate mechanistically on these findings it is important to mention that adenosine, released by ectonucleotidase activities (including ENPP1), is known to be an inhibitory mediator of T effector lymphocytes in various immune diseases." (PMID 31318911, 2019).
autosomal recessive disease (1 paper, 2014). Autosomal recessive form of disease. "Mutations in the gene encoding NPP1 (Enpp1) have been associated with a rare autosomal recessive disease generalised arterial calcification of infancy (GACI)." (PMID 25260930, 2014).
ENPP1 also shares sentences with these, for which no sentence is quoted: autosomal dominant hypophosphatemic rickets (13 papers); arterial calcification of infancy (8); Glucose intolerance (5); X-linked hypophosphatemia (5); pancreatic cancer (4); Stroke (4); hereditary hypophosphatemic rickets (3); Hypercalciuria (3); Impaired glucose tolerance (3); multiple myeloma (3); osteosarcoma (3); Hearing impairment (2); Hyperinsulinemia (2); hypoglycaemia (2); lipodystrophy (2); lung squamous cell carcinoma (2); otitis media with effusion (2); Raine syndrome (2); thrombocytopaenia (2); autism (1); autism spectrum disorder (1); bacterial infections (1); beta thalassemia (1); brain cancer (1); bronchopneumonia (1); carcinoid (1); cardiac hypertrophy (1); cervical cancer (1); cervical squamous cell carcinoma (1); chronic myelogenous leukemia (1).
A further 55 diseases each share a sentence with ENPP1 in 1 paper.